FOXO1 (forkhead box O1)
Diseases named in the same sentence as FOXO1 in open-access papers (continued):
Sharing a sentence is not in itself a finding about the gene and the disease.
granulosa cell tumor (5 papers, 2016 to 2023). A slow-growing, malignant tumor, characterize by the presence of granulosa-like cells and Call-Exner bodies, that is almost always found in the ovary. "For instance, when Foxo1 and Foxo3 genes were selectively inactivated follicle development is impaired and granulosa cell tumor formation is increased in a mouse model." (PMID 29549247, 2018). "To further determine the molecular identity of tumors observed in TGFBR1CA; Amh-Cre mice, we conducted immunostaining using antibodies against three granulosa cell tumor-expressed protein markers including FOXL2, INHA, and FOXO1." (PMID 38067144, 2023). "At an early age, these mice demonstrated follicular defects and development of ovarian granulosa cell tumors, which were immunoreactive for granulosa cell markers including FOXL2, FOXO1, and INHA." (PMID 29221447, 2017). "We found that ovarian tumors from TGFBR1-CAAcre mice were immunoreactive for FOXL2, FOXO1, and INHA, supporting the development of granulosa cell tumors in these mice." (PMID 27344183, 2016).
muscular atrophy (5 papers, 2014 to 2024). "Specifically, the miR-486-5p found within MSC exosomes has been shown to act on Forkhead Box O1 (FOXO1), inhibiting both its nuclear localization and the expression of genes associated with muscular atrophy." (PMID 39066929, 2024). "It has been reported that, in the galactose injection induced aged mice model, low activated IRS1 or Akt and high activated FoxO1 associated with muscular atrophy could be improved by exercise remission, through the way of activated IRS1 and Akt, facilitated by the phosphorylation of FoxO1." (PMID 29271915, 2017). "By contrast, aerobic ET attenuated this change in FoxO expression; specifically, the effects of aerobic ET in phosphorylate FoxO1, contributing, at least in part, to the prevention of skeletal muscle atrophy." (PMID 25330387, 2014). "FOXO1 has been shown to regulate the differentiation of myotubes and the remodeling of skeletal muscle fiber types, thereby leading to the expression of Atrogin-1 and MuRF-1 proteins that are important to the development of skeletal muscle atrophy." (PMID 28407698, 2017).
oral cancer (5 papers, 2015 to 2022). "They showed that FOXO1 played a critical role in suppressing cellular growth mediated by quercetin in oral cancer cells with high EGFR expression." (PMID 35462903, 2022). "A recent study by Chan also indicated that HBP1 acted as a direct downstream target of FOXO1, and potently suppressed the phenotypes of oral cancer." (PMID 32850392, 2020). "Quercetin increased FOXO1 expression, resulting in induction of P21, leading to cell cycle arrest and apoptosis in oral cancer." (PMID 31731635, 2019). "FOXO1-induced activation of the 2-kb HBP1 promoter was also observed in HSC-3 oral cancer cells, and the induction was abolished when co-transfected with FOXO1-specific siRNA." (PMID 28099936, 2017). "Taken together, these data support HBP1 as a downstream target of FOXO1, which contributes to FOXO1-mediated inhibition of malignancy in oral cancer." (PMID 28099936, 2017). "The results indicated that HBP1 knockdown potently promoted malignant phenotypes of oral cancer and the suppressive effect of FOXO1 on cell growth, colony formation, and invasion was alleviated upon HBP1 knockdown in invasive oral cancer cells." (PMID 28099936, 2017). "In the present study, we further found that the PI3K inhibitor LY294002 significantly up-regulated HBP1 expression with a concomitant decrease in FOXO1 phosphorylation in HSC-3 oral cancer cells." (PMID 28099936, 2017). "Ectopic overexpression of constitutively active FOXO1 (FOXO1-AAA) significantly suppressed colony growth in HSC-3 oral cancer cells; however, HBP1 knockdown alleviated the suppressive effect of FOXO1-AAA on colony formation." (PMID 28099936, 2017). "Taken together, our data provide evidence for HBP1 as a direct downstream target of FOXO1 in oral cancer malignancy." (PMID 28099936, 2017). "Similarly, knockdown of FOXO1 expression with FOXO1-specific siRNA led to reduced HBP1 expression in TW206 oral cancer cells with high level of endogenous FOXO1." (PMID 28099936, 2017). "Indeed, when we tested the correlation between HBP1 and FOXO1 expression in aggressive oral cancer specimens, we found that HBP1 mRNA levels were positively correlated with FOXO1 mRNA levels in invasive oral cancer." (PMID 28099936, 2017). "Hence, we studied whether FOXO1 activation of the HBP1 promoter is also under the control of the upstream regulator Akt in the HSC-3 oral cancer cell line with an aberrant activation of the EGFR/PI3K pathway." (PMID 28099936, 2017). "Here, we showed that HBP1 can function as a downstream effector of FOXO1-mediated growth inhibition in oral cancer; HBP1 knockdown alleviated the suppressive effect of FOXO1 on colony formation." (PMID 28099936, 2017). "Ectopic expression of FOXO1 led to increased HBP1 promoter activity and HBP1 expression in oral cancer cells." (PMID 28099936, 2017). "To illustrate FOXO1 regulation of HBP1 expression in oral cancer, first, we examined if HBP1 expression levels are in concert with FOXO1 levels." (PMID 28099936, 2017). "Together, the current study provided evidence that FOXO1 and HBP1 function coordinately as tumor suppressors in invasive oral cancer." (PMID 28099936, 2017). "Hence, the current study is aimed at investigating the putative transcriptional regulation of HBP1 by FOXO1 and, collectively, the biological significance of FOXO1 and HBP1 in oral cancer." (PMID 28099936, 2017). "Furthermore, both FOXO1 and HBP1 mRNA levels were significantly lower in three EGFR over-expressing oral cancer cells tested than the normal human oral keratinocyte (HOK)." (PMID 28099936, 2017). "These clinical data suggest that a combination of low HBP1 and low FOXO1 status might determine oral cancer malignancy, and that HBP1 and FOXO1 expression might be coordinately regulated." (PMID 28099936, 2017). "Next, we examined whether FOXO1-mediated expression of HBP1 modulates tumorigenic growth and metastatic potential in oral cancer." (PMID 28099936, 2017).
oral cancer (continued). "In the current study, we found a decreased FOXO1 mRNA level in invasive oral tumor specimen, and the combination of decreased mRNA expression levels of FOXO1 and HBP1 may predict invasiveness of oral cancer." (PMID 28099936, 2017). "Furthermore, the biological significance of FOXO1-mediated HBP1 expression was demonstrated by the experiments of colony formation and cell invasion in oral cancer cells." (PMID 28099936, 2017). "Subsequently, a recent report illustrated that HBP1 is direct target of growth factors-mediated PI3K/Akt/FOXO pathway in various types of cancer; however, whether or not FOXO1 regulates HBP1 expression in oral cancer remains unclear." (PMID 28099936, 2017). "However, the relationship between FOXO1 and HBP1 in oral cancer remains unclear." (PMID 28099936, 2017).
pancreatic ductal adenocarcinoma (5 papers, 2015 to 2021). An infiltrating adenocarcinoma that arises from the epithelial cells of the pancreas. "A recent study reported that viral ectopic expression of FOXO1 in ductal pancreatic adenocarcinoma cells upregulates LINC01197 (LETR1), resulting in the inhibition of cell proliferation." (PMID 33568674, 2021). "We have previously shown that miR-21 regulates cancer cell growth via FoxO1 in pancreatic ductal adenocarcinoma (PDAC)." (PMID 26068418, 2015). "Transcription factor forkhead box protein O1 (FOXO1) as another direct substrate of FTO, regulates gluconeogenesis in liver and promotes the growth of pancreatic ductal adenocarcinoma." (PMID 31142332, 2019). "Furthermore, cancer stem cells (CSCs) in pancreatic ductal carcinoma are FOXO1-negative, and the loss of FOXO1 might be a more accurate CSC marker than the expression of CD133 or ALDH1." (PMID 27924058, 2017).
periodontal disease (5 papers, 2019 to 2024). "Alterations in FoxO1 function have a significant effect on periodontal disease susceptibility because FoxO1 is involved in the regulation of leukocyte function." (PMID 36233176, 2022). "Alterations in FOXO1 function have a significant effect of periodontal disease susceptibility and due to FOXO1 regulation of leukocyte function." (PMID 31849924, 2019). "FOXO1 is an essential parameter of the antioxidant system that plays a role in the pathogenesis of periodontal disease, and this role should be elucidated in further studies." (PMID 38658396, 2024). "However, no study confirms FOXO1 as a therapeutic agent in periodontal disease." (PMID 38658396, 2024). "However, they have not yet addressed whether FOXO1 induces formation and activity of specific CD4+ T-helper cell phenotypes or the formation and activity of CD8+ lymphocytes that may affect resistance or susceptibility to periodontal disease." (PMID 31849924, 2019).
polycystic ovary syndrome (5 papers, 2014 to 2024). A disorder that manifests as multiple cysts on the ovaries. "SIRT3 plays a key role in oocyte maturation and alleviates polycystic ovary syndrome by modulating the FOXO1/PGC-1α+β signaling pathway." (PMID 39595642, 2024).
preeclampsia (5 papers, 2021 to 2025). Preeclampsia is a hypertensive disorder of pregnancy that is characterized by new-onset hypertension with proteinuria presenting after 20 weeks of gestation, and depending on mild or severe forms may initially present with severe headache, visual disturbances, and hyperreflexia. "Of note, alterations in FOXO3a and FOXO1 expression and activity have been associated with preeclampsia, a pregnancy-related complication characterized by impaired EVT invasion and migration." (PMID 41450565, 2025). "As mentioned, HDAC9 alters the acetylation status of FOXO1, promoting its activation; therefore, some deleterious cellular complications in preeclampsia may be a consequence of FOXO1 dysregulation secondary to the loss of HDAC9." (PMID 41416997, 2025). "Hence, dysregulation of FOXO3a and FOXO1 has been associated with poor pregnancy outcomes, such as preeclampsia and gestational diabetes mellitus." (PMID 41450565, 2025). "The mean maternal serum FoxO1 levels were significantly lower both in early-onset (9.1 ± 3.8 vs. 29.1 ± 3.2, p < 0.001) and late-onset preeclampsia (2.6 ± 1.6 vs. 29.1 ± 3.2, p < 0.001) than the normotensive pregnancies." (PMID 39808389, 2025). "The threshold value for maternal serum FoxO1 in predicting preeclampsia < 3.64 ng/mL, and the area under the curve (AUC) was 0.951 (95% confidence interval (CI) 0.82–0.93, 0.875, p > 0.001 with 78.8% sensitivity and 76.5% specificity)." (PMID 39808389, 2025). "Reduced integrin β3 and FOXO1 levels were detected in placental samples isolated from preeclampsia patients when compared to healthy controls." (PMID 41450565, 2025). "Nonetheless, considering FOXO1 is essential for proper placental development and the presence of hypoxic stress in preeclampsia, global FOXO1 inhibition would likely be detrimental during pregnancy." (PMID 41416997, 2025). "The mean maternal serum FoxO1 level of late-onset preeclampsia was significantly lower than the early-onset preeclampsia group (2.6 ± 1.6 vs. 9.1 ± 3.8, p < 0.001)." (PMID 39808389, 2025). "Furthermore, a significant decrease in FOXO1 serum concentrations was correlated with the onset of preeclampsia." (PMID 41450565, 2025). "Sirtuins and FoxO1 are reported to be important in the pathophysiology of preeclampsia." (PMID 39808389, 2025). "The ROC curve analysis of maternal serum SIRT2 and FoxO1 concentration for predicting preeclampsia." (PMID 39808389, 2025). "Similarly, FOXO1 was reported to be poorly expressed in the placenta of preeclampsia patients in comparison to the control group." (PMID 41450565, 2025). "Down-regulated FOXO1, which effected by oxidative stress, could impaired trophoblast adhesion and migration via mediating expression of integrin β3 in preeclampsia." (PMID 37853336, 2023). "Thus, based on our data along with previous reports, it is tempting to speculate that parasite-driven repression of FOXO3a- and FOXO1-regulated transcriptional programs and biological processes in EVTs contribute to pregnancy-related pathologies, including preeclampsia." (PMID 41450565, 2025). "Up-regulated FOXO1 would enhance migration and invasion, and inhibit apoptosis of trophoblast through activating AKT signaling pathway thus for alleviating preeclampsia." (PMID 37853336, 2023). "FoxO1 and SIRT2 may be biomarkers for early detection of preeclampsia and potential therapeutic targets in the pathophysiology of preeclampsia." (PMID 39808389, 2025). "The difference in FoxO1 and SIRT 2 serum levels in early- and late-onset preeclampsia does not seem to be related to the gestational week but probably to the different pathophysiologic basis of these two conditions." (PMID 39808389, 2025).
preeclampsia (continued). "This study aimed to investigate whether serum FoxO1 and SIRT2 concentrations differ between preeclampsia and normal pregnancy and also to compare these markers in early- and late-onset preeclampsia." (PMID 39808389, 2025).
squamous cell carcinoma (5 papers, 2017 to 2025). A carcinoma arising from squamous epithelial cells. "The results showed that the high FOXO1 expression levels significantly elevated the survival probability among head and Neck squamous cell carcinoma patients (n = 255) (HR, 0.61 (0.38–0.98), log-rank P = 0.041), reducing the death risk up to 39% over three year period." (PMID 41436994, 2025).
alcoholic liver diseases (4 papers, 2021 to 2023). A disorder caused by damage to the liver parenchyma due to alcohol consumption. "According to our data, miR-183-5p targets FOXO1, SMAD4, and GSK3B genes involved in transcriptional misregulation in cancer, FOXO signaling pathway and alcoholic liver disease." (PMID 37168369, 2023).
Anxiety (4 papers, 2019 to 2023). Intense feelings of nervousness, tension, or panic often arise in response to interpersonal stresses. "In the same way, decreased FOXO1 levels in the brain were associated with reduced levels of anxiety in mice, being suggested as a regulator of the anxiety-like phenotypes." (PMID 37891184, 2023). "Brain-specific deletion of Foxo1 driven by the Nestin promoter results in increased anxiety in a forced swim test, contrary to the reduced anxiety in Foxo3-deficient mice." (PMID 34727995, 2021). "This study further indicated that mice displayed reduced anxiety when FoxO1 was knocked down in the brain." (PMID 31281445, 2019). "Additionally, it was observed that FOXO1 and FOXO3 could be potential targets in anxiety and mood disorders." (PMID 37891184, 2023).
Arthritis (4 papers, 2021 to 2023). Inflammation of a joint. "MiR-182 positively mediates T helper cell proliferation by suppressing forkhead box O1 expression, and its inhibition prevents T helper cells from inducing arthritis." (PMID 33468167, 2021). "Next, a deep histological analysis of intracellular IGF1R signalling in spleen of arthritis mice was performed by staining IRS1 and FOXO1." (PMID 36105797, 2022).
autism (4 papers, 2018 to 2025). Persistent deficits in social interaction and communication and interaction as well as a markedly restricted repertoire of activity and interest as well as repetitive patterns of behavior. "The 16p13.3 region and the RBFOX1 gene have been implicated in autism; FOXO1 is a transcription factor; and ST6GALNAC3 is expressed in the reproductive tract." (PMID 29434669, 2018). "In summary, our findings demonstrate that Rg1 counters VPA‐induced autism‐like behaviors—ranging from repetitive actions to impaired sociability—by modulating Sirt2/Foxo1 expression and reducing neuroinflammation and oxidative damage." (PMID 40622845, 2025). "This study investigated whether Ginsenoside Rg1 (Rg1) alleviates autism‐like behaviors in mice prenatally exposed to valproic acid (VPA) via Sirt2/Foxo1 signaling." (PMID 40622845, 2025). "Here, we show significant downregulation of the transcription factors FOXO1 and HAND2 in neurons from 15q duplication, but not AS deletion subjects suggesting that disruptions in transcriptional regulation may be a driving factor in the autism phenotype in Dup15q syndrome." (PMID 29423132, 2018).
B-cell acute lymphoblastic leukemia (4 papers, 2017 to 2024). A neoplasm of lymphoblasts committed to the B-cell lineage, typically composed of small to medium-sized blast cells. "Dual specificity tyrosine phosphorylation regulated kinase 1 A (DYRK1A) promoted the development of B-cell acute lymphoblastic leukemia through the phosphorylation of FOXO1." (PMID 38795132, 2024). "A recent study in precursor B-cell acute lymphoblastic leukemia revealed that pre-BCR signaling regulates PI3K/AKT, FOXO1 and MYC and can be a target of SYK inhibition." (PMID 28212447, 2017).
bone tumor (4 papers, 2015 to 2024). "The immunocytochemistry assay results showed that HIF-1α and FoxO1 protein expression was significantly increased in bone cancer tissues compared with normal adjacent tissues." (PMID 31905813, 2019). "The 2ΔΔCt values of HIF-1α and FoxO1 were significantly increased in bone cancer tissues relative to normal adjacent tissues (p < 0.05)." (PMID 31905813, 2019). "Next, we measured FOXO1 expression in OS through immunohistochemical analysis, with osteoid osteoma (a benign bone tumor) used as a control." (PMID 26344693, 2015).
chronic lymphocytic leukemia (4 papers, 2020 to 2025). "Another piece of evidence supporting FoxO1‐targeted therapy comes from the field of chronic lymphocytic leukemia." (PMID 39533662, 2025). "Chronic lymphocytic leukemia (CLL) represents another malignancy of mature B cells where FoxO1 has tumor‐supporting functions." (PMID 39533662, 2025). "We describe a non-genetic adaptation to BTK inhibitor therapy in chronic lymphocytic leukemia that involves Akt activation via FoxO1/Rictor axis." (PMID 39436708, 2024).
classical Hodgkin lymphoma (4 papers, 2013 to 2023). "Also, increased miR-96, miR-182 and miR-183 downregulate the expression of FOXO1 transcription factor in classical Hodgkin lymphoma (cHL) cell lines, suggesting that decreased FOXO1 expression is involved in lymphomagenesis." (PMID 32309538, 2013). "Therefore, FOXO1 acts as a tumor suppressor in various solid tumors and classical Hodgkin lymphoma." (PMID 36675119, 2023). "It has been shown that FOXO1 is highly expressed in normal germinal center B cells and is not expressed in classical Hodgkin lymphoma (cHL), and ectopic expression of a constitutively active FOXO1 induces apoptosis in cHL cell lines and blocks proliferation." (PMID 24205217, 2013).
clear cell renal cell carcinoma (4 papers, 2019 to 2022). "ADAMTS9-AS2 inhibits cell proliferation via the miR-27a-3p/FOXO1 axis in clear cell renal cell carcinoma and controls the chondrogenic differentiation in human mesenchymal stem cells through a ceRNA mechanism." (PMID 33526083, 2021).
Impaired glucose tolerance (4 papers, 2013 to 2020). An abnormal resistance to glucose, i.e., a reduction in the ability to maintain glucose levels in the blood stream within normal limits following oral or intravenous administration of glucose. "Overexpression of FoxO1 or FoxO6 in mouse liver causes elevated fasting blood glucose levels and impaired glucose tolerance." (PMID 24015318, 2013). "The activation of Foxo1 and gluconeogenesis in the liver may have contributed to the impaired glucose tolerance of STZ male offspring." (PMID 31308441, 2019). "Transgenic overexpression of FoxO1 in the β-cells results in defective GSIS and impaired glucose tolerance in mice." (PMID 32184820, 2020).